CDH1 (cadherin 1)
Diseases named in the same sentence as CDH1 in open-access papers (continued):
Sharing a sentence is not in itself a finding about the gene and the disease.
cancer (continued). "In 2004, we initiated a prospective study to perform total gastrectomy on patients with CDH1 truncating, but not missense, mutations, irrespective of whether or not they had a preoperatively diagnosed cancer." (PMID 35158993, 2022). "Here, we performed a targeted sequencing panel of 324 cancer‐related genes (including ABL1, BCL2, CDH1, EGFR, etc.)at an average depth of 500× in all the specimens to identify mutations in genes that may be pivotal for synchronous primary cancer (BioProject accession number: PRJNA761143)." (PMID 36128740, 2022). "Importantly, we found that the frequency of P/LP CDH1 variants in multiple cancer types did not vary according to ethnicity for the most part." (PMID 34949788, 2022). "While there is potential for dasatinib-AKT inhibitor combinations to be useful clinically, the similar level of synergy in both WT and CDH1−/− cells suggests that this combination may not increase the available therapeutic index between normal cells and early CDH1-null cancers." (PMID 35406381, 2022). "Other cancers (non-gastric) are described in association with the CDH1 gene germline alterations." (PMID 34066044, 2021). "Overall, the evidence is lacking to support routine enhanced cancer screening, especially colorectal, in CDH1 mutation families, unless there is a family history of first- and second-degree relatives with a colorectal histopathology showing a mucinous component and/or signet-ring cells." (PMID 34073553, 2021). "Thus, the HNSCC hypermethylated CDH1 gene, involved in cell-cell adhesion, could be considered as a good biomarker for distinguishing cancer tissues from potentially premalignant oral lesions and from healthy oral mucosa." (PMID 32961999, 2020). "CDH1 accretion may also promote cancer development and progression." (PMID 32805721, 2020). "Additionally, the importance of DAPK and CDH1 in cancer has been revealed." (PMID 33066747, 2020). "However, deletion and mutations of Cdh1 are not frequent events in most human cancers (cBioPortal.org), suggesting that post-transcriptional and post-translational mechanisms suppress the E3 ligase activity of APCCdh1." (PMID 31420536, 2019). "Also, other genes identified as crucial for cancer progression, including E-cadherin (CDH1), von-Hippel-Lindau (VHL), protein kinase D1 (PKD1), maspin, cysteine-rich protein with Kazal motif (RECK) or urokinase-type plasminogen activator (uPA) were found to be regulated via DNA methylation." (PMID 30103412, 2018). "We provide evidence that a cancer-associated SNP influences this paRNA-based regulatory network by modifying the secondary structure of the sense transcript within the miRNA/AGO1 binding region, thereby increasing the accessibility of the miRNA/AGO1 complex to the paRNA and the CDH1 promoter." (PMID 28555645, 2017). "Following dPCR quantification of the canonical transcript, we could demonstrate that CDH1 was significantly less expressed in cancer tissue compared to normal mucosa of the same patients (P = 0.001); this downregulation was especially evident (at least 1.5 times less) in 76% of IGC tumors." (PMID 27861150, 2017). "The following family members who are all currently healthy with no cancer were positive for the CDH1 c.172G>T mutation: the proband's mother (70‐years‐old), brother (47‐years‐old), maternal aunt (57‐years‐old), and two daughters (aged 29 and 39‐years‐old), and maternal grandfather (93‐years‐old)." (PMID 27064202, 2016). "This study expands the non-anaphase-promoting complex/cyclosome function of Cdh1 in regulating the NEDD4 family E3 ligases, and further suggested that enhancing Cdh1 to inhibit the E3 ligase activity of WWP2 could be a promising strategy for treating human cancers." (PMID 27462441, 2016). "The reduction of CDH1 expression may involve in invasion and metastasis of several cancers." (PMID 27067410, 2016).
cancer (continued). "Also, the PTEN tumor suppressor gene was shown to stimulate association of Cdh1 with the APC/C, and hence, the frequently observed loss of PTEN may indirectly result in impaired APC/C-Cdh1 function in cancers." (PMID 26650195, 2016). "An important note in this context of CDH1 gene expression in our chosen five cell lines is the presence of wild-type (no mutations) CDH1 gene sequences as determined from the publicly available database at the cancer cell lines encyclopedia (CCLE) of the Broad institute." (PMID 27303212, 2016). "Therefore, inducing Cdh1 abundance may present a potential therapeutic approach for the treatment of human cancers with high E3 ligase activity of WWP2." (PMID 27462441, 2016). "The spread of disease in many cancers has been linked to the expression of EMT transcription factors, which lead to an invasive phenotype characterized by low expression of epithelial marker E-cadherin (CDH1) and high expression of mesenchymal markers Vimentin (VIM) and N-cadherin (CDH2)." (PMID 25605241, 2015). "Genes including E-cadherin (Cdh1, up), amphiregulin (Areg, down), c-Met/hepatocyte growth factor receptor (Met, down) and c-Myc (Myc, down) were notable examples of genes involved in cell growth, differentiation and cancer that were significantly regulated by Tcf7l2 silencing." (PMID 25414334, 2014). "Our results suggest that the presence of the CDH1 rs1801552 TT genotype is associated with a two-fold decreased risk for NSCL/P in the investigated population, but further studies with larger cohorts from different populations and taking into account family history of cancer are warranted." (PMID 24838934, 2014). "Based on the important role of CDH1 in cancer tumorigenesis, the investigation of the regulatory mechanisms of CDH1 in the process of primary to metastatic NB transition may highlight new prognostic markers and therapy targets for the metastasis of NB in the future." (PMID 24520301, 2014). "Analysis of human cancer datasets confirms that elevated WNT gene expression is associated with high levels of CUX1 and GLIS1 and correlates with genes of the epithelial-to-mesenchymal transition (EMT) signature: VIM, SNAI1 and TWIST1 are elevated whereas CDH1 and OCLN are decreased." (PMID 25217618, 2014). "Reexpression of Cdh1 might counteract migration and metastasis of cancer cells." (PMID 19636430, 2009). "Therefore, Skp2 upregulation in most human cancers might be due to a synergistic action of upregulated Skp2 mRNA levels with a concomitant evasion of Cdh1-mediated degradation." (PMID 19549334, 2009). "Germline mutations in CDH1 and TWIST1 may be associated with inherited cancer susceptibility." (PMID 19493342, 2009). "This study proposed a putative axis of piR-823/PIWIL1/DNMT3B/CDH1 that appears to be involved in EMT and cancer stemness in OC, providing a basis for future mechanistic studies." (PMID 41596471, 2026). "High DNMT3B expression is associated with silencing of tumor suppressor genes, such as E-cadherin (CDH1), the promotion of EMT, the maintenance of cancer stemness, and chemoresistance." (PMID 41596471, 2026). "CDH1 not only promotes aerobic glycolysis but also inhibits OXPHOS and promotes angiogenesis for nutrient transport, a phenomenon commonly observed in cancer." (PMID 41020695, 2025). "Cancer cells undergo the epithelial-to-mesenchymal transition (EMT) process, resulting in a decrease in the expression of ZO-1 and CDH1." (PMID 41375475, 2025).
cancer (continued). "CDH1 and VIM protein levels changed similarly, and CD44s protein levels, overexpressed in cancer stem cells and during EMT, were partially depleted upon DOX stimulation indicating MET." (PMID 39759848, 2025). "By binding to the promoter of the CDH1 (E‐cadherin) gene, SNAIL1, SNAIL2, and ZEB2 suppress CDH1 expression and increase CDH2 (N‐cadherin) levels, reducing cell adhesion and promoting mesenchymal traits such as increased motility and invasion in cancer cells." (PMID 41244070, 2025). "While Program-1 was enriched with genes from a pan-cancer EMT program, it also notably included epithelial differentiation genes such as CDH1, IRF6, JUP, KLF6, and TJP2." (PMID 40777467, 2025). "First, we noted that CDS1-high cancer cells express high levels of the epithelial marker gene E-cadherin (CDH1), whereas CDS1-low cancer cell lines express mesenchymal markers like ZEB1, ZEB2 and vimentin (VIM) 48,49." (PMID 40615674, 2025). "The expression levels of ACBD3 are positively correlated with epithelial marker E-Cadherin (CDH1) and negatively correlated with mesenchymal marker Vimentin (VIM) or Zinc Finger E-Box Binding Homeobox 1 (ZEB1) in TCGA LUAD cohort and cancer cell lines." (PMID 40189704, 2025). "Accordingly, the reduction in CDH1 mRNA expression in ELIT-exposed luminal mammospheres further supports the involvement of EMT, a process that facilitates cancer cell dissemination and invasion." (PMID 39767718, 2024). "During the development of aggressive cancer, the epithelial-to-mesenchymal transition (EMT), characterized by a change in the expression from E-cadherin (CDH1) to N-cadherin (CDH2), enables cancer cells to acquire invasive and metastatic properties." (PMID 38675711, 2024). "Instead, a high expression of NANOG and Zeb-1 and an expression of CDH-1, similar to that detected in ground control cells characterized BR95 cancer cells, well identify their mesenchymal character." (PMID 39451527, 2024). "In addition, they also describe that the in vitro studies indicate that loss of CDH1 expression or function can trigger the activation of transcription factors linked to epithelial–mesenchymal transition (EMT), a process that contributes significantly to the occurrence of metastasis in cancer cells." (PMID 39728992, 2024). "The treatment of cancer cells with DBMSCs in the IC setting modulated the expression of various factors with a specific role in cellular adhesion, including AKT1, CALD1, CDH1, FN1, and STAT3." (PMID 39768220, 2024). "The JUN family and FOS family activities were up-regulated in the resistant cells, which had been proven to regulate E-cadherin (CDH1), N-cadherin (CDH2), and SNAIL2 expression in cancers." (PMID 39732719, 2024). "Various epithelial markers including epithelial cell adhesion molecule (EpCAM), cadherin 1 (Cdh1), keratin (Krt) 5/14, desmoglein 2 (Dsg2), and epithelial splicing regulatory protein 1/2 (Esrp1/2) have been adopted to depict the EMT states of cancers." (PMID 37654227, 2023). "Collectively, these data indicated that FAK activation was related to ROS1 inhibitor (crizotinib)-resistance in CDH1-deficient cancer cells, and that FAK inhibition could thus overcome this drug resistance, ultimately leading to synergistic therapeutic effects in these cancers." (PMID 37324948, 2023). "We therefore evaluated the expression of a panel of epithelial (KRT5, 7, 8, 18, and CDH1), mesenchymal (VIM, FN1, SNAI1, TWIST1, COL1A1, and PRRX1), and cancer stem cell (ALDH1A2, ALDH7A1, CD44, and CCND1) markers in all samples." (PMID 36980717, 2023).
cancer (continued). "The most altered cancer-related genes include NBN, RAD51C, BRIP1 (mostly with amplification events), and CDH1 (usually with losses or deep deletions)." (PMID 37239898, 2023). "Genes differing insignificantly from healthy tissue were IMP-3, CDH1, IQGAP1, NEDD9, TKS5, WAS and ARPC4, indicating minimal alterations in their expression levels in the analyzed cancer samples." (PMID 37623256, 2023). "Due to its role in down-regulating E-CADHERIN (CDH1) expression, ZEB1 is commonly known as a driver of EMT, cancer progression and metastasis formation." (PMID 38139138, 2023). "KMT2D and GATA3 were uniquely identified in African Americans as cancer drivers reported in TCGA data, whereas PIK3CA, MAP3K1, CDH1, and MUC6 were identified in Caucasians." (PMID 37454130, 2023). "Based on our above findings of p-FAK upregulation under ROS1 inhibitor resistance, we next tested whether inhibiting FAK activity could restore the negative impact of ROS1 inhibitors on cancer cell proliferation in vitro using CTG assays in the five CDH1-deficient cell lines." (PMID 37324948, 2023). "EMT is initiated by snail, a key transcription factor, which inhibits E-cadherin/CDH1 expression and promotes cancer metastasis." (PMID 38313074, 2023). "Metastasis requires mesenchymal changes in the epithelial cancer cells, which are characterized by higher expression of mesenchymal markers like vimentin (VIM) and a decrease in the epithelial markers like E-cadherin (CDH1)." (PMID 37934721, 2023). "It is worth noting that all mentioned genes affect CDH1 expression which is controlled by SMARCA5, a stem cells differentiation gene and cancer marker." (PMID 37972206, 2023). "Similar to NUP98, NUP88 is overexpressed in a variety of human cancers, and, in this state, it sequesters the NUP98-RAE1 complex in the cytoplasm away from APC/CDH1, disturbing mitotic checkpoint control and promoting aneuploidy." (PMID 36835439, 2023). "The inclusion of CDH1 in HBOC and gastrointestinal gene panels, recommended by the French Genetic and Cancer Consortium, has led to the identification of increasing numbers of families with lobular cancer without DGC but also in incidental findings." (PMID 37761816, 2023). "We have found that the most altered cancer-related genes include NBN, RAD51C, BRIP1 (mostly with amplification events), and CDH1 (usually with losses or deep deletions)." (PMID 37239898, 2023). "Increased CDH3 expression also increases cell motility and migration in cancer by interfering with CTNND1 and CDH1." (PMID 37151391, 2023). "MutSigCV analysis identified CDC27, PIK3CA, GATA3, CDH1, CTBP2, and CRIPAK as common cancer driver genes across both Ki67 expression groups (ZF13)." (PMID 37454130, 2023). "The zinc finger protein SNAI1 (also known as Snail; UniProt/Swiss-Prot: O95863, gene name SNAI1), represses the expression of a broad repertoire of epithelial genes, including E-cadherin/CDH1, and is a master regulator of EMT in most cancers." (PMID 36765041, 2023). "For example, several proteins were pan-cancer markers present in EVs from nearly all PDX models, including ALB, C1QBP, CDH1, and PKM." (PMID 36470535, 2023). "Genetic testing for CDH1 GPVs, and soon to include CTNNA1 GPVs, is available for affected individuals who meet the set clinical criteria whereby at least one cancer is histologically confirmed." (PMID 37258796, 2023). "We detected cancer cells using markers typical of LUAD and alveolar epithelium (EPCAM, CDH1, KRT19, KRT18, KRT8)." (PMID 37745301, 2023). "As EMT is a common process that has been postulated to be responsible for carcinoma cell metastasis, the effect of the BCSC secretome on the expression of epithelial markers (CDH1, TJP1 and OCLN) and mesenchymal markers (Snail, FN1, MMP2 and VIM) was assessed." (PMID 36915147, 2023).
cancer (continued). "EMT is a phenomenon in which the infiltration capacity is strengthened by showing a decrease in the E-cadherin (CDH1) expression involved in cell adhesion and an increase in vimentin (VIM) expression, which is a mesenchymal marker, in cancer." (PMID 35330413, 2022). "E-cadherin, also known as CDH1, is an important cancer suppressor, and its poor expression is allied with EMT, which is known to accelerate cancer cell migration and invasion." (PMID 36118880, 2022). "Another transcriptome profiling study in Chinese patients with GC revealed 36-fold higher expression of CDH1, while DPT and TGFBR2 showed decreased expression in cancer samples." (PMID 35625299, 2022). "For example, CDH1 is an important marker of EMT and is often down-regulated or inactivated during the progression of cancers." (PMID 35656554, 2022). "We used pan-cancer expression data to find 14-LncRNAs that had a high correlation with the EMT markers VIM, CDH1, FN1, SNAI1, and SNAI2." (PMID 36120580, 2022). "These include: CDH1, MUC1, THBS4, and MSLN for PEs related to cancer; ADA2, CXCL10, and WARS for TB-PEs; CRP, S100A9, and VIM for parapneumonic PEs; and C9, LDHA, HPX, LDHB, and C3 for benign-PEs." (PMID 35197508, 2022). "Studies have not yet assessed whether CDH1 is a cancer-susceptibility gene in other cancers." (PMID 34949788, 2022). "When tumors promote cancer cell invasion and metastasis through the EMT pathway, CDH1 and Vimentin are often downregulated, while CDH2 is overexpressed." (PMID 35657638, 2022). "We compared the mRNA abundance of all WNT downstream MMP members and CDH1 in normal, OLP, and cancer tissues using our previous data (GSE70666)." (PMID 35850748, 2022). "Previous studies have shown that WT1 can promote cancer progression by regulating target genes, such as p21, SLUG, and CDH1." (PMID 35915803, 2022). "One of these epithelial markers is E-Cadherin (CDH1), which is commonly described together with the mesenchymal marker VIM in the epithelial-mesenchymal transition during development and cancer." (PMID 35789843, 2022). "CDH1 has the highest degree value in PPI network and was significantly overexpressed in BC tissues, consistent with its overexpression in multiple human cancers." (PMID 36131343, 2022). "In particular, we expect that CDH1 will be studied in the future to determine how it regulates the occurrence and development of ACP through the pathways in cancer signaling pathway." (PMID 36387067, 2022). "ZNF217 stimulates cancer cell migration, invasion and epithelial–mesenchymal transition (EMT) by negative regulation of CDH1/E-cadherin expression." (PMID 36551531, 2022). "Inactivation of CDH1 decreases cell-cell adhesion and activates a couple of oncogenic signaling pathway such as RhoA signaling, Wnt, and MAPK pathways, promoting cancer metastasis and recurrence." (PMID 36317124, 2022). "The urine proteome profile of PCa and cancer-free subjects was analyzed by two software packages and 18 dysregulated proteins, of which 5 (TTR, EFEMP1, CDH1, SECTM1, KLK3) common to both software, were found." (PMID 35454907, 2022). "Similar to other carcinoma, in EC various tumor suppressor gene promotors (MLH1, PTEN, p16, APC, MGMT, RASSF1, PR and CDH1) are hypermethylated, whereas oncogene promotors (BMP, CTCFL, PARP1, CASP8) are hypo- or demethylated." (PMID 35284957, 2022). "It has been shown that certain PRC2 subunits target CDH1, whereas BMI1 through linking to Twist is essential for EMT initiation and the acquisition of the cancer stem cell (CSC) phenotype." (PMID 33572395, 2021).